SRA1 (steroid receptor RNA activator 1)
Description:
Functional RNA which acts as a transcriptional coactivator that selectively enhances steroid receptor-mediated transactivation ligand-independently through a mechanism involving the modulating N-terminal domain (AF-1) of steroid receptors. Also mediates transcriptional coactivation of steroid receptors ligand-dependently through the steroid-binding domain (AF-2). Enhances cellular proliferation and differentiation and promotes apoptosis in vivo. May play a role in tumorigenesis.
Synonyms: SRAP; PP7684; SRA; STRAA1
Tractability: Antibody: its Gene Ontology location is reachable by antibodies, with high confidence. PROTAC: ubiquitination databases record sites on it; its protein half-life has been measured.
Gene: Protein-coding gene on chromosome 5 (140,537,340 to 140,557,677, reverse strand). Ensembl gene ENSG00000213523.
Subcellular location: Nucleus; Cytoplasm
Subcellular location (Human Protein Atlas): Nucleoplasm; Cytokinetic bridge; Cytosol; Microtubules; Primary cilium
Gene Ontology:
Molecular function: protein binding; steroid receptor RNA activator RNA binding; transcription coactivator activity
Biological process: negative regulation of myoblast differentiation; regulation of transcription by RNA polymerase II; positive regulation of DNA-templated transcription
Cellular component: cytoplasm; cytosol; nucleoplasm; nucleus; ribonucleoprotein complex
Genetic constraint (gnomAD): Loss-of-function variants: 25 observed, 22.98 expected, observed/expected ratio (o/e) 1.09, 90% interval 0.79 to 1.52. The upper end of that interval is the gene's LOEUF score, 1.52, which puts it in group 6 of 6, group 1 being the genes least tolerant of losing a copy. Missense variants: 297 observed, 288.4 expected, observed/expected ratio (o/e) 1.03, 90% interval 0.94 to 1.13. Synonymous variants: 103 observed, 111.98 expected, observed/expected ratio (o/e) 0.92, 90% interval 0.78 to 1.08.
Homologues: Orthologues: chimpanzee SRA1 (99% identical), guinea pig SRA1 (87% identical), mouse Sra1 (82% identical), dog SRA1 (82% identical), rat Sra1 (81% identical), pig SRA1 (79% identical), zebrafish sra1 (46% identical), tropical clawed frog sra1 (45% identical).
Diseases named in the same sentence as SRA1 in open-access papers:
SRA1 is named in the same sentence as 71 diseases in open-access papers, as found by Europe PMC text mining. Sharing a sentence is not in itself a finding about the gene and the disease. The quoted sentences say what the papers report.
atherosclerosis (15 papers, 2016 to 2025). A disease characterized by the build-up of fatty material and calcium deposition in the arterial wall resulting in partial or complete occlusion of the arterial lumen. "Previous experiments have shown that disruption of the SRA1 or CD36 pathway partially inhibits the uptake of acetylated-LDL (Ac-LDL) or ox-LDL by macrophages while delaying the progression of atherosclerosis in hypercholesterolemic mice." (PMID 35966555, 2022). "Formononetin, an AM component, alleviated atherosclerosis in ApoE-/- mice by regulating the interaction between krüppel-like factor 4 (KLF4) and steroid receptor RNA activator 1 (SRA)." (PMID 35267929, 2022).
breast carcinoma (14 papers, 2009 to 2024). "In contrast, a recent case study evaluated the association between breast cancer risk and two haplotype tagging SNPs (htSNPs) (rs10463297, rs801460) within the SRA1 locus." (PMID 30238005, 2018). "Sra1 is an estrogen- and androgen-dependent gene that contributes to the progression of breast cancer in women." (PMID 37623890, 2023). "Of note, a long non-coding RNA, steroid receptor RNA activator 1 (SRA1), has been experimentally validated to play roles in a variety of cancer types, including breast cancer, prostate cancer, and liver cancer." (PMID 33596182, 2021). "But there is a potential relationship between SRA1 and breast cancer, SRA RNA expression is altered during breast tumorigenesis." (PMID 31867043, 2019). "The semantic similarity between gastric cancer and breast cancer is very large, perhaps future research could explain the relationship between SRA1 and gastric cancer." (PMID 31867043, 2019). "SRA1 is a steroid receptor activator, involving in the regulation of many nuclear and non-nuclear receptors and associating with breast cancer." (PMID 24884718, 2014). "PUS1 plays a role in the interaction between steroid receptor RNA activator 1 (SRA1) with the retinoic acid receptor-gamma (RARG) and the estrogen receptor in melanoma and breast cancer cells, respectively." (PMID 33430133, 2021). "Breast cancer-related genes from GAD were also identified as ESR1 interactors, including TP53BP1, SRA1, and BBS4." (PMID 33987091, 2021). "For example, PUS1 mediates the interaction of steroid receptor RNA activator 1 (SRA1) with retinoic acid receptor-γ (RARγ) in melanoma cells, and with oestrogen receptor in breast cancer cell lines." (PMID 33461542, 2021).
Obesity (6 papers, 2020 to 2024). Accumulation of substantial excess body fat. "Regression analysis stratified by obesity status revealed the independent association of adipose SRA1 expression with MyD88 in NW (N = 12), and with TLR9 in overweight (N = 32) participants." (PMID 36552771, 2022). "Overall, our data demonstrate a direct association between the AT SRA1 expression and the TLRs together with their downstream signaling partners and IRFs in individuals with obesity and/or T2D." (PMID 36552771, 2022). "In fact, SRA1 is now known to be associated with several diseases, including obesity, cardiovascular diseases, polycystic ovary syndrome (PCOS), laryngeal squamous cell carcinoma, and breast cancer." (PMID 34685582, 2021). "Overall, our data showed varying association patterns of adipose SRA1 expression with the metabolic profile of individuals, differing with regard to the obesity and T2D status." (PMID 34685582, 2021). "Based on our knowledge, the level of SRA1 expression in the AT in obesity and its association with insulin resistance and metabolic inflammation in humans in a clinical setting are poorly understood." (PMID 34685582, 2021). "In conclusion, AT SRA1 expression is elevated in people with obesity which associates with typical immunometabolic markers of obesity/T2D, implying that SRA1 may have potential as a biomarker of metabolic derangements." (PMID 34685582, 2021). "Since SRA1 AT expression in obesity/type 2 diabetes (T2D) and the relationship with immune-metabolic signatures remains unclear, we assessed AT SRA1 expression and its association with immune–metabolic markers in individuals with obesity/T2D." (PMID 34685582, 2021). "Sra1+/− and Sra1−/− mice appeared normal, and Sra1−/− mice were shown to be resistant to high-fat-diet-induced obesity." (PMID 37987303, 2023). "Our data further show that TLR3/TLR9 expression was associated independently with the expression of SRA1 in individuals with T2D, while TLR3, TLR7 and IRAK1 were identified as the independent predictors of adipose SRA1 expression in individuals with obesity." (PMID 36552771, 2022). "Taken together, TLR3 remains the independent predictor of adipose SRA1 expression in settings of both obesity and T2D." (PMID 36552771, 2022). "In the present study, we show that the adipose tissue SRA1 protein expression is significantly increased in individuals with obesity, as compared to their normal weight counterparts, regardless of T2D status." (PMID 36552771, 2022). "Steroid receptor RNA activator gene (SRA1) emerges as a player in pathophysiological responses of adipose tissue (AT) in metabolic disorders such as obesity and type 2 diabetes (T2D)." (PMID 36552771, 2022). "Overall, these data support the plausibility of adipose SRA1 expression to be considered as a novel, surrogate biomarker of adipose inflammation in obesity/T2D." (PMID 36552771, 2022). "Based on our knowledge, this is the first study investigating the level of expression of SRA1 in the AT in humans with obesity/T2D." (PMID 34685582, 2021). "In conclusion, we show for the first time that SRA1 adipose expression is elevated with obesity in humans, which correlates with specific metabolic parameters and/or adipose tissue immune markers." (PMID 34685582, 2021). "Regarding the obesity status, independent associations were found only for TNF-α and CCR2 with SRA1 expression in NW (n = 12), and overweight (n = 32) participants." (PMID 34685582, 2021). "In humans, the level of SRA1 adipose expression and its relationship with clinical and immunometabolic signatures of obesity and T2D are poorly understood." (PMID 34685582, 2021). "Steroid receptor RNA activator 1 (SRA1) is involved in pathophysiological responses of adipose tissue (AT) in obesity." (PMID 34685582, 2021). "Since SRA1 adipose tissue expression was elevated in obesity, we next sought to determine the relationship of SRA1 expression with the inflammatory cytokines/chemokines in our study population." (PMID 34685582, 2021).
Obesity (continued). "For example, the whole-body knockout mice of the lncRNA steroid receptor RNA activator 1 (Sra1) are resistant to high fat diet-induced obesity, with decreased epididymal and subcutaneous white adipose tissue (WAT) mass, and increased lean content (i.e., decreased percent of body fat)." (PMID 36672953, 2023). "In the current study, we examined whether the human adipose tissue SRA1 expression associated with TLRs expression, their adaptor proteins and TLR-downstream signaling molecules including NF-κB, IRF3, 4, and 5 in obesity and/or T2D." (PMID 36552771, 2022). "Furthermore, TLR3/TLR7/IRAK1 and TLR3/TLR9 were identified as independent predictors of AT SRA1 expression in individuals with obesity and T2D, respectively." (PMID 36552771, 2022). "Our results support the opinion that adipose expression of SRA1 may be viewed as a potential new biomarker of obesity in humans, but caution should be considered in generalizing these findings as our study is limited by certain caveats." (PMID 34685582, 2021). "A potential link between elevated SRA1 expression and typical correlates of obesity/T2D implies that SRA1 may have significance as a potential new biomarker of metabolic disorders." (PMID 34685582, 2021). "We therefore asked whether obesity and T2D affected the expression of SRA1 in the adipose tissue." (PMID 34685582, 2021). "In individuals with obesity (N = 64), TLR3, TLR7 and IRAK1 were detected as the independent predictors of adipose SRA1 expression." (PMID 36552771, 2022). "Third, our data also lack information of the SRA1 and SRA protein (SRAP) expression in main insulin target tissues other than white subcutaneous adipose tissue in obesity." (PMID 34685582, 2021). "SRA1 expression associated with TLR2, IRAK1, and IRF3 expression only in individuals with obesity, regardless of diabetes status." (PMID 36552771, 2022). "While SRA1 mRNA expression is significantly elevated, only in people with obesity people without T2D as compared to normal-weight counterparts." (PMID 36552771, 2022). "In conclusion, our data show that the AT SRA1 expression correlates with TLRs-3,4,7,9, MyD88, NF-κB, and IRF5 expression in individuals with T2D and with TLR2, IRAK1, and IRF3 expression in individuals with obesity." (PMID 36552771, 2022). "We also reported that the adipose SRA1 expression was higher in non-diabetic persons with obesity compared with non-diabetic lean participants, and that the changes associated directly with BMI, PBF, fasting serum insulin, HOMA-IR, certain inflammatory markers but inversely with HbA1c level." (PMID 36552771, 2022). "In a knock-out mouse model of SRA1 has displayed improved insulin sensitivity and resistance to developing obesity under high-fat diet conditions, but obesity and T2D themselves might have a non-significant influence on SRA1 expression levels, reflecting a plausible absence of reverse causation." (PMID 34685582, 2021). "We sought to determine SRA1 protein expression in adipose tissue samples from NW individuals and those with obesity, 10 individuals each, and the data show that the expression was significantly higher in people with obesity compared to their NW counterparts, whether with or without T2D (p < 0.0001)." (PMID 36552771, 2022).
prostate carcinoma (5 papers, 2001 to 2024). A carcinoma that arises from epithelial cells of the prostate gland. "Based upon our proposed method, prostate cancer was predicted to be associated with H19, MALAT1, CDKN2B-AS1, HOTAIR, PCAT1, SRA1, XIST." (PMID 29671405, 2018). "Indeed, since the knockdown of the SRA1 gene depletes both SRA and SRAP, future experiments are required to distinguish the functions of SRA and SRAP in the pathogenesis of prostate cancer." (PMID 30238005, 2018).
hepatocellular carcinoma (4 papers, 2021 to 2024). A malignant tumor that arises from hepatocytes. "Previously, SRA1 has been suggested to predict hepatocellular carcinoma(HCC) development due to its significant association with tumor size and serumglucose level, indicating that SRA1 may be a novel biomarker of HCC." (PMID 39076490, 2024). "In this study, We found that SRSF1 regulates the alternative splicing of SRA1 to promote the migration of hepatocellular carcinoma cells." (PMID 34011971, 2021). "In summary, our results provide experimental evidence that SRA1 exon 3 inclusion is up regulated by SRSF1 to promote tumor invasion and metastasis in hepatocellular carcinoma." (PMID 34011971, 2021). "In cell invasion, knockdown of SRA1-L significantly decreased the invasive ability of hepatoma cells while knockdown of SRA1-In1 had no significant impact." (PMID 34011971, 2021). "In this study, we found that SRSF1 can regulate the alternative splicing of SRA1 in hepatocellular carcinoma cells, but the specific mechanism is not clear." (PMID 34011971, 2021). "In hepatocellular carcinoma (HCC), SRSF1 promotes tumor infiltration and subsequent metastasis by regulating the alternative splicing of SRA1." (PMID 39336772, 2024).
cardiomyopathy (3 papers, 2014 to 2024). A disease of the heart muscle or myocardium proper. "SRA1 was reported tobe a cardiomyopathy risk factor and was linked with cardiac myofibroblastactivation." (PMID 39076490, 2024). "The pathogenesis and development ofchronic heart failure (CHF) may involve long non-coding ribonucleic acid (lncRNA)steroid receptor RNA activator 1 (SRA1), a known cardiomyopathy risk factor andregulator of cardiac myofibroblast activation." (PMID 39076490, 2024).
cervical squamous cell carcinoma (3 papers, 2020 to 2021). A squamous cell carcinoma arising from the cervical epithelium. "detected the downregulation of SRA1 in patients with HPV-negative cervical squamous cell carcinoma, but not HPV-positive patients." (PMID 33997099, 2021).
depression (3 papers, 2022 to 2024). "One SNP variant, the intronic deletion in steroid receptor RNA activator 1 (SRA1) gene (rs60236323), had an OR < 1 with a variant allele frequency of 50.7% in non-depression EM patients and 37.5% in depression EM patients." (PMID 36704746, 2022). "Therefore, changes in SRA1 expression may contribute to sex-dependent vulnerability to developing these diseases as both depression and AD are approximately twice as prevalent in women." (PMID 38862462, 2024). "Many of these genes have been previously linked to brain-related disorders, including Alzheimer’s disease (WDR12, AGFG2, and CDK5RAP3), schizophrenia (SRA1, WDR55, CORO7, DDAH2, PCDHA8), autism spectrum disorder (MAPK3, PCDHA13), and major depressive disorder (ZMAT2 and ITIH4)." (PMID 39269986, 2024). "The overlapping eQTL genes between AD and depression (SRA1, MICA, PCDHA8, PCDHA10, PCDHA7, and PCDHA13), were not yet associated with these disorders through proximity analysis nor have an established role in these diseases as of yet." (PMID 38862462, 2024).
diabetes (3 papers, 2021 to 2023). "Our data showed increased cholesterol uptake genes (FABP1, CD36, and SRA1) in diabetes, which was in an agreement with recently published studies." (PMID 36829889, 2023). "We also observed inflammatory markers (IL-8, TNF-α and CCL2) protein expression was positively correlated with SRA1 protein expression in individuals with diabetes." (PMID 34685582, 2021). "SRA1 associated with waist circumference in people without diabetes and NW participants, whereas it associated inversely with HbA1c in overweight participants." (PMID 34685582, 2021). "In people without diabetes SRA1 expression was associated with CCL3 (r = 0.298, p = 0.036), CCL8 (r = 0.344, p = 0.021), CXCL11 (r = 0.400, p = 0.003), TNF-α (r = 0.317, p = 0.030), TGF-β (r = 0.514, p < 0.0001), IL13 (r = 0.310, p = 0.028), and IL18 (r = 0.547, p < 0.0001)." (PMID 34685582, 2021). "TNFα also predicted SRA1 adipose expression in both normal weight and obese populations, regardless of diabetes status." (PMID 36552771, 2022). "TNF-α also predicted SRA1 adipose expression in both NW and obese populations, regardless of diabetes status." (PMID 34685582, 2021). "We observed that inflammatory markers (TNF-α and IL-18) protein expression was positively correlated with SRA1 protein expression in individuals without diabetes." (PMID 34685582, 2021). "TGF-β/IL18 independently predicted the SRA1 expression in people without diabetes and in the total study population, while TNF-α/IL-2RA predicted SRA1 only in people with diabetes." (PMID 34685582, 2021). "TGF-β and IL18 in people without diabetes and TNF-α and IL2RA in people with diabetes were independent predictors of SRA1 expression." (PMID 34685582, 2021). "SRA1 expression associated with BMI, PBF, serum insulin, and HOMA-IR in the total study population and people without diabetes." (PMID 34685582, 2021). "We speculate that the negative association between these factors and adipose SRA1 expression in the absence of diabetes factor imparts tenacity to the positive relationship of these factors with SRA1 expression in the cohort with diabetes." (PMID 36552771, 2022). "TNF-α also predicted SRA1 in both NW and obese people regardless of the diabetes status." (PMID 34685582, 2021). "Besides, TGF-β and IL18 independently predicted the SRA1 expression in non-diabetics as well as in the total (diabetic and non-diabetic) study population, while TNF-α and IL-2RA were the independent predictors of SRA1 only in people with diabetes." (PMID 34685582, 2021).
glioma (3 papers, 2016 to 2024). A benign or malignant brain and spinal cord tumor that arises from glial cells (astrocytes, oligodendrocytes, ependymal cells). "Summarizing the MR results presented in the heatmap, we observed that SRA1, SCDF1, SLC25A24, ZSCAN23, and ZSCAN26 were notably associated with glioma risk across at least two cell types, with consistent MR estimates, indicating potential cross‐cell effects of these genes." (PMID 39722126, 2024).
liver cancer (3 papers, 2020 to 2021). An epithelial or non-epithelial malignant neoplasm that arises from the liver. "Overexpression of the SRA1 gene is also associated with breast, ovarian, prostate, lung and liver cancer." (PMID 32942630, 2020). "Both isoforms of SRA1 play vital roles in cell invasion and migration and serve as prognostic biomarkers and therapeutic targets for liver cancer." (PMID 34011971, 2021). "Expression of SRA1 was found to significantly increase in liver cancer." (PMID 34011971, 2021). "To find the potential splicing factors regulating the alternative splicing of exon 3 of SRA1, firstly, using public datasets from UALCAN24, we examined the connection between the expression of splicing factors and the major cancer stages of liver cancer." (PMID 34011971, 2021).